ALK (ALK receptor tyrosine kinase)
Diseases named in the same sentence as ALK in open-access papers (continued):
Sharing a sentence is not in itself a finding about the gene and the disease.
tumor (continued). "Further, treatment with a 2,4-pyrimidinediamine derivative with a median inhibitory concentration for ALK of 10 nM and a high specificity to ALK was effective in significantly reducing tumor burden by ~30%." (PMID 22928112, 2012). "The emergent knowledge of molecular tumor profiles e.g., EGFR and KRAS mutations and ALK rearrangements for instance raises logistic and algorithmic considerations to approaching the molecular management of the adenocarcinoma subtype of NSCLC." (PMID 25562798, 2012). "For this, the respective gene expression arrays of surgical tumor specimen at the time of diagnosis were searched for the levels of PTN or ALK mRNA." (PMID 23267434, 2012). "ALK-positive tumours have been detected in all histological subtypes of adenocarcinoma, but especially in solid signet-ring cell and mucinous cribriform patterns." (PMID 22825000, 2012). "The intracellular kinase domain of ALK fuses with the N-terminal of EML4, and then encodes a cytoplasmic chimeric protein with kinase activity, which subsequently drives tumor growth." (PMID 23109866, 2012). "Use of a break-apart ALK FISH probe is an effective method for assessing ALK gene rearrangement status in routinely submitted formalin fixed paraffin-embedded NSCLC tumor samples from a wide variety of tissue sources and clinical settings." (PMID 23198868, 2012). "Some discordant results have been observed in tumours expressing ALK with a weak (1+) to moderate (2+) signal." (PMID 22825000, 2012). "One aspect of Hsp90 biology that is largely unstudied in ALK-expressing tumours is the role of Hsp90 co-chaperones." (PMID 22681779, 2012). "The invasive capability of cells is a hallmark of malignancy and we thus studied the contribution of ALK signaling to tumor cell invasion of an endothelial monolayer." (PMID 23267434, 2012). "Only a subset of tumor cells in anaplastic lymphoma kinase (ALK)+ ALCL expresses FOXP3, and the level of expression varies among tumor cells, pointing to an intricate mechanism of FOXP3 regulation." (PMID 22151904, 2011). "Inhibition of ALK-activity resulted in sustained tumor regression in the xenotransplant tumor model." (PMID 21494621, 2011). "The novel tumour group comprised high-stage 11q-deleted tumours with low expression of ALK and MYCN, but high expression of various CNS and nervous system developmental genes." (PMID 21492432, 2011). "ALK gene rearrangements and the resulting fusion proteins in tumor specimen can be identified by fluorescent in situ hybridization (FISH), immunohistochemistry (IHC), and reverse transcription-polymerase chain reaction (RT-PCR)." (PMID 21504625, 2011). "With either variant, a tumor sample is considered to be positive when more than 15% of the tumor cells are positive for the ALK fusion gene." (PMID 21785682, 2011). "Activation of the ALK proto-oncogene is required for tumor transformation, through the induction of several downstream pathways which control key cellular processes such as cell-cycle progression, survival, cell migration and cell shaping." (PMID 20957039, 2010). "Therefore, i) PHOX2B and ALK mutations are involved either in the initiation or the progression of NB and ii) wild-type as well as mutated transcripts of both these genes are reported to be overexpressed in the vast majority of the NB cell lines and tumor samples analyzed." (PMID 20957039, 2010). "Both neoplasms apparently were derived from immature lymphohematopoietic progenitor (stem) cells and both were found to express ALK." (PMID 21297223, 2010). "Studies of familial cases of NB allowed for identification of two NB susceptibility genes (ALK, PHOX2B) yet their mutations are present in about 10% of sporadic tumours." (PMID 20003389, 2009). "BP7033Br ALK was more efficient in inhibiting tumor cell proliferation, migration and survival when compared to BP7033Br." (PMID 19262688, 2009).
tumor (continued). "Both BP7033Br and BP7033Br ALK inhibited about 80% the D3H2LN tumor growth after intratumoral injection of about 286 μg BPs per mouse twice a week during 21 days." (PMID 19262688, 2009). "A second area of amplification was found in one tumor at chromosome 2p23, the site of the anaplastic lymphoma kinase (ALK) gene on the 10K array." (PMID 17327916, 2007). "This approach appears feasible also for human NB cells since NB tumours express CTL-defined TAA, such as tyrosine hydroxylase (, MAGE-1 and 3, NY-ESO and ALK, and tumour-specific cytolytic T lymphocytes have been isolated from NB-bearing patients." (PMID 15150552, 2004). "This case suggests that chemotherapy may enrich ALK fusion-positive tumour cell clones through selective pressure." (PMID 41737422, 2026). "This difference was likely due to the smaller number of indications in our analysis (23 vs. 69), the smaller patient sample size, a focus on several smaller tumors (i.e., ALK+), and using Flatiron Health to estimate tumor type-specific market shares, lines of therapy, and biomarker status." (PMID 41325138, 2026). "This prognostic difference may be closely associated with the characteristics of the collagen fiber-dominated microenvironment in the tumor stroma and the standardized use of ALK inhibitors after surgery." (PMID 41200062, 2026). "The presence of myxoid features and ALK immunoreactivity might be mistaken for an ALK-rearranged neoplasm, particularly the recently described ALK-rearranged superficial myxoid neoplasms." (PMID 40748380, 2025). "Fourth, other important prognostic and biological factors—such as molecular tumor profiles (EGFR, KRAS, ALK mutations), PD-L1 expression, or systemic inflammatory indices beyond NLR/PLR/LMR—were not incorporated into the analysis, potentially limiting mechanistic interpretation." (PMID 41010912, 2025). "Although various mutations are associated with upregulation of PD-L1 expression in tumor cells, the mechanisms of decreased efficacy of ICI on EGFR-and ALK-driven NSCLC remains unclear." (PMID 40809430, 2025). "The discrepancy between trends shown by our results and known effect of rs1129055 on immune system activation may be also explained by the expression of CD86 by ALK-positive ALCL tumor cells." (PMID 41469691, 2025). "Finally, we analyzed serial tumor biopsies from ALK‐positive tumor treatments to understand resistance mechanisms and found three potential patterns of mutational dynamics under treatment pressure." (PMID 40168046, 2025). "Additionally, we evaluated the effect of AC484 on primary tumor cells isolated from the pleural effusion of an ALK+ ALCL patient and observed that AC484 markedly increased apoptotic cells." (PMID 40734623, 2025). "To determine whether there is inter-tumor variability in the anti-apoptotic response to ALK-TKIs, we also explored anti-apoptotic adaptations in the H2228 cell line." (PMID 40113795, 2025). "This may be influenced by factors such as radiotherapy dose, the type and concentration of ALK inhibitors, and the biological characteristics of tumor cells." (PMID 41458607, 2025). "Immunohistochemical analysis revealed that the tumor was ALK-positive." (PMID 40224630, 2025). "We further assessed whether ALK+ tumor cells expressing CD4 or CD8 also expressed CD44 or CD62L markers, usually used to distinguish naïve (CD62Lhigh CD44low), effector (CD62Llow CD44high) or central memory T cells (CD62Lhigh CD44high)." (PMID 40175628, 2025). "The constitutive active NPM1::ALK tyrosine kinase drives tumor transformation." (PMID 41469691, 2025). "The presence of ALK gene rearrangement results in propensity to spread tumor cells to the CNS." (PMID 40227844, 2025). "Notably, ALK mutations often co-occur with MYCN amplification, and this co-alteration appears to synergistically facilitate tumor initiation and progression." (PMID 41614760, 2025).
tumor (continued). "With the aim of deepening the knowledge of immune-based mechanisms that might influence tumor onset and relapse in ALK-positive ALCL patients, we assessed 14 genetic variants of 13 genes potentially involved in the anti-tumor immune response in 180 patients." (PMID 41469691, 2025). "We remain steadfast in our efforts to exploit ALK as a tumor-restricted antigen by developing an ADC with a humanized ALK-directed antibody with cross-species reactivity to decrease immunogenicity risk, and with conjugation to a cytotoxic payload with maximal potency and a physically stable linker." (PMID 40813394, 2025). "The patient's rapid response to alectinib suggests that the relapsed tumor is still ALK-driven." (PMID 40054123, 2025). "A total of 33 ALK TKI-resistant tumor samples were collected from 35 patients." (PMID 40674592, 2025). "Tumor cells may develop resistance to the drug by up-regulating the copy number of the ALK gene, thereby counteracting its inhibitory effect." (PMID 40584293, 2025). "Moreover, they evaluated the effects of ALK TKIs and demonstrated that these inhibitors effectively hinder tumor progression." (PMID 41275415, 2025). "Furthermore, immunization with ALK peptides or cDNA has been effective prophylactically and therapeutically in mouse models of ALK‐rearranged tumours." (PMID 40351161, 2025). "Indeed, in a previous study, we identified several hundred differentially acetylated proteins, including chromatin-modifying proteins and transcription factors, in mouse NPM::ALK tumor cell lines depleted for HDAC1." (PMID 40175628, 2025). "Phenotypic transformation represents a critical mechanism of resistance to ALK inhibitors, characterized by tumor cells undergoing lineage reprogramming to shift from an ALK-dependent phenotype to alternative cellular states, thereby evading the selective pressure imposed by targeted therapy." (PMID 41614760, 2025). "Crizotinib binds to the ALK kinase domain, inhibiting tumor cell proliferation and survival." (PMID 39941694, 2025). "However, Western blot analysis revealed no detectable ALK in any of the liver tumor models, ruling out the possibility that the anti-tumor effect of ceritinib is mediated through ALK inhibition." (PMID 40968384, 2025). "Further advancements for the reliable detection of genomic alterations leading to ALK inhibitor resistance from the peripheral blood via liquid biopsies analyzing cell-free DNA fragments (cfDNA)/circulating tumor DNA (ctDNA) are urgently warranted for optimal treatment guidance." (PMID 38960389, 2025). "Beyond classical ALK on-target mutations, tumor resistance involves a spectrum of “noncanonical” mechanisms." (PMID 41614760, 2025). "Notably, the expression of HDAC1 and HDAC2 was comparable between ALK+ tumor cells and other immune cells, including T cells, B cells, and NK cells, suggesting that class I HDACs are abundant in normal and malignant immune-cell subsets." (PMID 40175628, 2025). "Since the ability of CAF-CM to promote the growth of ALK-inhibited tumor spheroids implied a significant contribution of CAF-derived soluble factors to tumor cell resistance, further analyses focused on investigating paracrine signaling pathways as a route of intercellular communication." (PMID 40524253, 2025). "Furthermore, next-generation sequencing (NGS) of a 425-gene panel (ALK, EGFR, RET, MET, KRAS, etc.)was conducted to identify the patient’s mutated genes, microsatellite instability (MSI), and tumor mutational burden (TMB)." (PMID 40071084, 2025). "However, the tumor cells exhibited round cell morphology in RanBP2 and ALK gene rearrangements cases." (PMID 40224630, 2025). "Aberrant ALK activation generally results from structural alterations or dysregulated expression, leading to persistent activation of downstream signaling pathways that drive tumor cell proliferation, survival, and metastasis." (PMID 41614760, 2025).
tumor (continued). "Furthermore, ALK rearrangements often respond well to ALK inhibitors, enabling tumor reduction and more conservative surgical approaches." (PMID 39796742, 2025). "We propose defining favorable and unfavorable features, such as histology, type of ALK fusion, co-existing molecular alterations, plasma circulating tumor DNA (ctDNA, performance status, and brain metastases, to help identify patients with lower and higher risk of progression." (PMID 40649750, 2025). "Furthermore, AC484 exhibits strong potent anti‐tumor activity against ALK+ ALCL by disrupting mitochondrial function and inhibiting mitophagy." (PMID 40734623, 2025). "The ALK (D5F3) companion diagnostic test was negative (tumor cells, positive control + negative control)." (PMID 41383499, 2025). "Tumor tissue samples from initial diagnosis and first relapse in the fourth patient (patient P4) were previously analyzed by targeted sequencing, reporting a partial ALK gain." (PMID 39760332, 2025). "KRAS mutations, unlike EGFR and ALK, are associated with a history of smoking, high PD-L1 expression, and a high tumor mutational burden (TMB)." (PMID 40558308, 2025). "Furthermore, sensitization of resistant tumor spheroids to ALK inhibition can be achieved not only through metabolic reprogramming via SREBP-1 inhibition but also by direct pharmacological induction of ferroptosis." (PMID 40524253, 2025). "One possible explanation involves the tumor microenvironment (TME) in NSCLC with certain genetic alterations, such as EGFR or ALK, which have been associated with reduced immunogenicity and often exhibit lower tumor mutational burden (TMB) and decreased neoantigen load." (PMID 40961974, 2025). "Additionally, IHC staining using the D5F3 clone (Ventana, Oro Valley, Arizona) showed diffuse cytoplasmic expression of ALK in the cytoplasm of tumor cells." (PMID 40054123, 2025). "Understanding ALK immunogenicity may provide insights into tumor-host interactions and contribute to the development of novel therapeutic strategies." (PMID 40255897, 2025). "In addition, ALK-positive ALCL patients respond to ALK-derived HLA-DRB1 (human leukocyte antigen DR beta 1 chain)-restricted peptides suggesting tumor recognition by CD4+ T cells." (PMID 41469691, 2025). "Immunohistochemically, all EIMS tumor cells are positive for ALK." (PMID 40282503, 2025). "Some studies suggest that DF may represent a true neoplasm, as evidenced by consistent ALK expression and ALK gene rearrangements in epithelioid DF, as well as gene fusions involving PRKCB and PRKCD, which have been detected across various DF subtypes." (PMID 40235691, 2025). "Studies have shown that PD-L1 expression is significantly elevated in patients with ALK-targeted therapy resistance, which may enable tumor cells to evade immune detection and elimination." (PMID 40873540, 2025). "However, due to the complexity of intracellular signaling networks, tumor cells frequently develop resistance, leading to the activation of alternative pathways that bypass ALK inhibition." (PMID 40873540, 2025). "Additionally, NGS analysis of the residual tumor tissue detected the presence of dual ALK arrangement—ELMOD3-ALK (E8: A20) fusion and EML4-ALK (E13: A20) fusion." (PMID 40297141, 2025). "In addition, the ALK fusion genes have been identified as tumor driver genes and potential therapeutic targets, and targeted therapy with ALK inhibitors, such as lorlatinib and alectinib, exhibited favorable antitumor activity in IMTUB with ALK fusion." (PMID 40386559, 2025). "When DCTN1 undergoes a gene fusion with ALK, it may lead to the abnormal activation of the ALK kinase, thereby promoting the proliferation and survival of tumor cells." (PMID 41246301, 2025).
tumor (continued). "In addition, tumor growth suppression and survival rates were improved substantially in both orthotopic RDAA NSCLC cell line-derived and patient-derived xenograft tumor models following ALK inhibitor (crizotinib or ceritinib) treatment." (PMID 40246819, 2025). "However, resistance to ALK inhibitors can emerge as a result of treatment or preexist as subclones within the tumor prior to therapy." (PMID 40064818, 2025). "With the clinical approval and widespread application of ALK inhibitors such as Crizotinib, Alectinib, and Ceritinib in the treatment of ALK-positive malignancies, these agents have demonstrated substantial efficacy in delaying tumor progression." (PMID 40872599, 2025). "Given the patient’s relatively advanced age at onset compared with previously reported cases, the tumor's aggressive growth, and the limited genomic data available for IMTs beyond ALK alterations, we performed WES to investigate potential novel genetic drivers of tumor progression." (PMID 40678018, 2025). "In addition, we revealed novel acute adaptive mechanisms in response to ALK inhibitors in cell lines and patient-derived tumor cells." (PMID 40113795, 2025). "Also, there was a good correlation between RNase1 and ALK phosphorylation through the tumor tissue IHC." (PMID 40246819, 2025). "One invalid test result was obtained using the IdyllaTM GeneFusion Assay, for which the reference reported an ALK fusion; the sample tested was however smaller (0–20 mm2) with low tumor cell content (10–20%) and confirmed to be a less-quality sample as commented to be indicative for RNA degradation." (PMID 38492039, 2024). "Subsequently, tumor progressed with an acquired EML4::ALK fusion." (PMID 38438731, 2024). "Furthermore, PF-02341066 was an ALK inhibitor that can induce autophagy in various tumor cell lines by inhibiting the STAT3 pathway." (PMID 38506898, 2024). "Interestingly, in ALK-rearranged tumor organoids, the drug sensitivity tests perfectly matched the clinical response observed for both untreated and treated patients." (PMID 39409152, 2024). "Because it was a germline mutation and therefore expected to be detectable in the patient’s blood at all time points regardless of tumor burden, this patient was excluded from the ALK mutation ctDNA analysis." (PMID 39177282, 2024). "This can occur due to factors such as the effects of anti-tumor therapies or the use of tyrosine kinase inhibitors that inhibit the activity of epidermal growth factor receptor (EGFR) or anaplastic lymphoma kinase (ALK)." (PMID 38462628, 2024). "ALK was initially identified as a fusion protein EML4-ALK, present as a rearrangement mutation in 5% of patients with NSCLC, and was marked as a driver tumor mutation in NSCLC." (PMID 38384472, 2024). "We compared EGFR‐positive and ALK‐positive tumors in a relatively homogeneous group, which may have clarified the tumor marker difference." (PMID 38400801, 2024). "Studies have shown that MET gene amplification can often coexist with other tumor driver genes in NSCLC, such as EGFR and KRAS mutations and ALK and ROS1 fusions, indicating that MET gene amplification may not act as an intrinsic driver factor within tumors." (PMID 39582541, 2024). "Research indicates that the specific fusion partner may influence tumor sensitivity to ALK inhibitors." (PMID 39906487, 2024). "Additionally, it is used as monotherapy for first-line treatment of adult patients with metastatic NSCLC whose tumors have a PD-L1 expression in ≥ 50% tumor cells or ≥ 10% tumor-infiltrating immune cells and lacks EGFR or ALK genomic tumor aberrations." (PMID 38384472, 2024). "Positive PD-L1 staining (P = .0426) and tumor mutational burden elevation (P = .0264), as well as KRAS mutations, were more frequent in the LITT + ICB group, while tumors were more frequently driven by EGFR or ALK in the LITT-only group (P = .0021)." (PMID 39717437, 2024).